GATA6 (GATA binding protein 6)
Diseases named in the same sentence as GATA6 in open-access papers (continued):
Sharing a sentence is not in itself a finding about the gene and the disease.
infection (7 papers, 2018 to 2025). The state of being infected such as from the introduction of a foreign agent such as serum, vaccine, antigenic substance or organism. "During infection, overall pleural immune-cell makeup was altered by the loss of GATA6." (PMID 36948193, 2023). "As deletion of GATA6 in myeloid cells negatively regulates PRM survival and aggregation formation, it is conceivable that GATA6 controls the MDR during infection." (PMID 35401237, 2022). "In this review, we will discuss the recent advances in the developmental origin, the phenotypic identity, and functions of PRMs, particularly the regulation of GATA6 in the pathobiology of PRMs during infection, injury, and tumorigenesis." (PMID 35401237, 2022). "MDR is a strategy to face and annihilate the infection by which macrophages, under the control of GATA6, move from the peritoneum to the closest tissues in order to alert the immune system." (PMID 34194430, 2021). "As LGR5 is required for efficient CM differentiation in hPSCs, we hypothesized that infection with a doxycycline (DOX)-inducible LGR5-expressing lentivirus might rescue the cardiac defects in GATA6-/- hESCs." (PMID 40080060, 2025). "To confirm our findings, we used a macrophage-specific deletion of the transcription factor, GATA6 (Gata6tm2.1Sad; Csf1rMeriCreMer), to test whether LPMs are required for increased infection during coinfection." (PMID 37847677, 2023). "GATA6, along with RA, controls TGF -β production in PRMs which is critical for gut-associated lymphoid tissue-independent IgA production by peritoneal B-1 cells to fight infection." (PMID 35401237, 2022). "Therefore, modulating GATA6 expression in PRMs may represent new therapeutic strategies for infection in the peritoneal cavity." (PMID 35401237, 2022). "Overall, these results are in agreement with the VAD experiments and demonstrate that GATA6 is required for HP-induced LPM expansion and HP-induced increased infection." (PMID 37847677, 2023). "Protein expression of the GATA6-dependent gene CD73 by LCMs matched our sequencing data, with LCMs from C57BL/6 mice having higher expression than BALB/c mice and infection leading to a further increase in CD73 expression in C57BL/6 LCMs but a complete loss in BALB/c mice." (PMID 36948193, 2023). "Infection of primary IFE keratinocytes with GATA6-expressing lentiviruses led to a dose-dependent increase in GATA6 mRNA, and to a significant GATA6 upregulation at the protein level." (PMID 33082341, 2020). "Thus successful integration of bmMΦ cells into the resMΦ niche is exemplified by expression of GATA6 and CD102, a process that is not altered by infection." (PMID 29299998, 2018).
adenocarcinoma (6 papers, 2015 to 2023). A common cancer characterized by the presence of malignant glandular cells. "A similar mechanism was recently described in H-1975 cells (a human adenocarcinoma cell line) where RA promotes the activity of GATA6, a transcriptional repressor, to down-regulate Ctnnb1 expression." (PMID 30568578, 2018). "In fact, amplification of GATA4 and GATA6 is often found in adenocarcinomas from other origins." (PMID 26555375, 2015).
heart disease (5 papers, 2019 to 2021). "ATAC-seq and GATA6 ChIP-seq analysis of GATA6 variant hiPSC-CMs reveals aberrant binding to congenital heart disease genes." (PMID 33054971, 2020). "Previous studies report that Gata4 and Gata6 are essential for heart development, and Hoxa1 mutant mice develop heart disease, suggesting a previously uncharacterized association between Hoxa1 and Gata4/6." (PMID 31147716, 2019).
gastrointestinal tumor (3 papers, 2008 to 2024). "More detailed studies are, however, required to establish the role of GATA-6 in the gastrointestinal tumor growth." (PMID 18405344, 2008).
GATA6 also shares sentences with these, for which no sentence is quoted: gall bladder (5 papers); cardiovascular diseases (3); Hypertension (3); adenomyosis (2); atypical endometrial hyperplasia (2); congenital heart malformation (2); Cornelia de Lange syndrome (2); diaphragmatic hernia (2); hypothyroidism (2); IPEX syndrome (2); tricuspid atresia (2); ) channelopathies (1); acute myocardial infarction (1); adult-onset diabetes (1); aortic valve disease (1); Arrhythmia (1); Arthritis (1); Atherosclerotic lesion (1); autoimmune conditions (1); Barrett adenocarcinoma (1); Bicuspid aortic valve (1); biliary atresia (1); biliary tract disorder (1); bladder tumors (1); brain cancer (1); cardia cancer (1); Cerebral ischemia (1); chronic obstructive pulmonary disease (1); Cirrhosis (1); cleidocranial dysplasia (1).
A further 68 diseases each share a sentence with GATA6 in 1 paper.